TNF (tumor necrosis factor)
Diseases named in the same sentence as TNF in open-access papers (continued):
Sharing a sentence is not in itself a finding about the gene and the disease.
Anxiety (continued). "An animal study found that acupuncture can inhibit TNF-α and promote the expression of IL-10 in the amygdala to improve the anxiety symptoms of patients with PD." (PMID 39588511, 2024). "We assessed lifespan, motor performance using balance and coordination tests, cognitive function through anxiety and memory tests, redox markers, and inflammation markers, particularly TNF-α and IL-6." (PMID 39656492, 2024). "Its daily application results in lower rates of disability and anxiety and lower levels of IL-8 and CD-80 on peripheral monocytes and TNF." (PMID 39337066, 2024). "Our findings demonstrate that SYN supplementation regulates the recovery of cardiac injury and depresses anxiety in conjunction with the suppression of the proinflammatory cytokine TNF‐α." (PMID 39264256, 2024). "Male mice exposed to an acute stressor showed elevated levels of TNF-α in the ventral hippocampus, concurrent with anxiety-like behavior." (PMID 38381770, 2024). "Accordingly, increased TNF‐α and IL‐6 levels simulated by LPS would increase anxiety and enhance the severity of cardiovascular injury." (PMID 39264256, 2024). "The peripheral rise in corticosterone in the first 3 h of LPS exposure promote the increase in IL-1β, IL-6, and TNF-α, exerting an anxiety effect on the limbic system, including the hippocampus." (PMID 39057053, 2024). "Genetic models of T2D, such as the db/db mice, also showed anxiety-like behavior, increased levels of inflammatory cytokines (IL-1β, TNF-α, and IL-6), and reduced levels of BDNF in the hippocampus." (PMID 38279738, 2024). "Collectively, our study highlights that the brain glial-derived CXCL16, promoting CXCR6+CD8+ T accumulation, acts on hippocampal neurogenesis and anxiety via TNF-α production." (PMID 39386089, 2024). "Given that the effects on anxiety and TNF-alpha levels were replicated in a second cohort at a lower dose, these effects are unlikely to be false positives." (PMID 39408292, 2024). "It has been demonstrated that treatment with fenofibrate significantly attenuated prenatal VPA-induced anxiety and low exploratory activity by reducing IL-6 and TNF-α in the prefrontal cortex." (PMID 39720795, 2024). "In our study, a correlation was observed between the increase in TNF‐α and IL‐6 levels and anxiety in hyperglycaemic rats on either diet." (PMID 39264256, 2024). "At this time, nuclear factor kappa-B, IL-1β, and tumor necrosis factor (TNF)-α in the brain will be significantly increased, promoting the anxiety state of mice, and administering L. reuteri can significantly improve this condition." (PMID 39076985, 2024). "Based on the previous studies and our current findings, it can be suggested that synbiotics appear to have anxiolytic effects on anxiety by regulating TNF‐α and IL‐6 levels, which are effective in anxiety formation." (PMID 39264256, 2024). "In the active disease group, the TNF-α level was lower in the anxiety group compared to the non-anxiety group." (PMID 37916198, 2023). "In VPA-induced ASD model mice, HRW administration improved ASD-like behaviors such as social behavior and pain sensation as well as anxiety-like behavior and memory impairment and IL-6 and TNF-α inflammatory cytokines." (PMID 36982559, 2023). "Compared to the remission group, TNF-α was significantly higher in patients with anxiety in the active disease group (11.67 pg/ml vs. 9.61 pg/ml, p-value 0.003)." (PMID 37916198, 2023). "TNF-α promotes the excitatory synaptic activity of PrLBLA neurons and induces anxiety-like behaviors." (PMID 36917193, 2023). "Further, central GPR120 agonist pre-treatment was effective in attenuating sickness- and anxiety-like behaviors triggered by systemic LPS and central TNF-α and IL-1β administration." (PMID 38111048, 2023). "This agrees with a case–control trial, where the authors demonstrated that abnormal levels of cytokines, including TNF‐α, were significantly correlated with the severity of depressive and anxiety mood symptoms." (PMID 36178333, 2023).
Anxiety (continued). "We provide multiple lines of evidence demonstrating that TNF-α in the PrL served as a trigger for elevated PrL-BLA circuit activity; this eventually was the cause of chronic pain–induced anxiety-like behaviors." (PMID 36917193, 2023). "Increase in anxiety like behavior, increase in Bacteroidetes, decrease in Firmicutes/Bacteroidetes ratio, increase in intestinal levels of IL-6, TNF-α, 5-HT, and decrease in corticotropin-releasing hormone, BDNF, and neuropeptide Y in the brain." (PMID 37324381, 2023). "Future investigations are required to define the contribution of TNF-α derived from distinct PrL cell types (individually or synergistically) to chronic pain-related anxiety-like behaviors." (PMID 36917193, 2023). "Collectively, these results imply that TNF-α specifically participates in the development of anxiety-like behaviors, probably through increasing excitatory synaptic activity and consequent neuronal activity of PrLBLA neurons." (PMID 36917193, 2023). "Increased levels of TNF-α were found in the dorsal–anterior cingulate cortex and the anterior insula of postmortem patients who presented with social rejection and increased anxiety." (PMID 37766304, 2023). "In our study, the TNF-α level in the anxiety symptom group in the active disease group was higher than in the remission group." (PMID 37916198, 2023). "TNF-α and IL-1β have been previously shown to induce anxiety-like behavior during the EPM test in rodents." (PMID 37432552, 2023). "Pregnant women with severe anxiety and accompanying depressive symptoms showed a significant increase in serum levels of IL-6 and TNF-α." (PMID 37637801, 2023). "Further, we report a critical role of TNF-α signaling in the PrL in mediating chronic pain–induced anxiety-like behaviors." (PMID 36917193, 2023). "Together, these data suggest that TNF-α was indispensable in regulating anxiety-like behaviors in mice with chronic pain through the upregulation of synaptic activity of PrLBLA neurons." (PMID 36917193, 2023). "Due to the link between anxiety and inflammation, expression of IL-1β, TNFα, and IFNγ genes was measured in the ileum and colon." (PMID 37960288, 2023). "In mouse models, it has been associated with increased levels of IL-6, TNF-α, and IFN-γ, a decrease in serotonin and dopamine levels within the hippocampus, induced loss of muscle strength and equilibrium, and increased anxiety and hopelessness." (PMID 38004391, 2023). "A recent study found that Poria cocos aqueous extract reduced inflammatory factors through the TNF-α/NF-κB signaling pathway and thereby improved SD-induced anxiety-like behavior." (PMID 37377643, 2023). "Thirdly, both blockade of TNF-α signaling with an antagonist and genetic deletion of Tnfa attenuated the anxiety-like behaviors in chronic pain." (PMID 36917193, 2023). "Firstly, TNF-α signaling and its protein level were increased in the PrL, and TNF-α expression positively correlated with anxiety level in both sham and SNI mice." (PMID 36917193, 2023). "To determine which receptor mediates the effects of TNF-α on excitatory synaptic activity and anxiety-like behaviors under chronic pain conditions, we first determined the expression of these receptors in PrLBLA neurons using single-cell RT-PCR analysis." (PMID 36917193, 2023). "This agrees with previous studies that demonstrated that anxiety-like behavior was associated with the increased mRNA expression of proinflammatory markers, including IL6, TNFα, NFkB, and MCP-1, in the hypothalamus and amygdala." (PMID 38201896, 2023). "In the active disease group, the TNF-α level was lower in the subjects experiencing anxiety symptoms but statistically insignificant (10.72 pg/ml vs. 11.17 pg/ml, p-value 0.383)." (PMID 37916198, 2023). "In animal studies, the activation of the microglia and the elevation of the pro-inflammatory factors IL-1α and TNF-α were evident in the mPFC of mice with anxiety induced by repeated social deficits." (PMID 36624089, 2023).
Anxiety (continued). "All of these results point to a fundamental role of TNF-α signaling in the PrL in mediating anxiety-like behaviors during chronic pain." (PMID 36917193, 2023). "Further, higher pre-existing subclinical anxiety symptoms significantly predicted a lower increase in anxiety after LPS administration, which was mediated by TNF-α." (PMID 36757901, 2023). "More importantly, the alteration of microbiota composition highly correlated with the elevated serum concentrations of TNF-α and LPS, as well as the anxiety symptom severity in patients with GAD." (PMID 36969214, 2023). "Blockade of TNF-α signaling in the PrL reverses chronic pain-related anxiety-like behaviors and synaptic deficits." (PMID 36917193, 2023). "The elevation of TNF in the hippocampus is intriguing as there is strong evidence to implicate the ventral hippocampus in the regulation of anxiety-like behaviour." (PMID 36104437, 2022). "Gastrointestinal tract inflammation instigates the liberation of pro-inflammatory cytokines, and increase in tumor necrosis factor-alpha (TNF-α) and interleukin 6 (IL-6) cytokines is linked directly with anxiety-like manifestations." (PMID 35433746, 2022). "TNF-α plays a vital role in the progression of cognitive decline as well as anxiety; targeting TNF-α signaling was effective in modulating anxiety in mice." (PMID 35741458, 2022). "In this recent study, an increase in the concentration of pro-inflammatory cytokines (TNF-α and IL-1β), inhibition of antioxidants enzymes (CAT, SOD) and GSH were associated with anxiety-like behaviour in diabetic rats treated with HAART." (PMID 35769902, 2022). "Direct microinjection of IL-1β or TNF-α into several brain regions induces anxiety-, depressive-like behavior, and cognitive dysfunction." (PMID 36051441, 2022). "Oxidative stress upregulates angiotensin-1 receptor levels and elevates NF-κB-mediated pro-inflammatory factors levels (IL-6, TNF-α) in these brain areas, leading to anxiety-like behaviors." (PMID 36761172, 2022). "Behavioral tests and biochemical analyses indicated that diabetic rats showed significantly increased anxiety and depressive-like behavioral deficits, brain oxidative stress and pro-inflammatory cytokines levels (IL-1β, IL-6 and TNF-α)." (PMID 35408607, 2022). "Pretreatment with losartan significantly improves FST performance and prevents LPS-induced anhedonia and anxiety-like behaviors in addition to preventing LPS-induced higher levels of the pro-inflammatory cytokine (TNF, IL-1, and IL-6)." (PMID 36761172, 2022). "To test the role of TNF in the expression of stress-induced behavioral change, we next examined the difference in stress-induced changes in anxiety-like behaviour between WT and TNF−/− mice." (PMID 36104437, 2022). "For example, chronic unpredictable stress induces both anxiety-like and depressive-like behaviors while increasing the expression of amygdala inflammatory cytokines, including IL-1β, IL-6, and TNF-α." (PMID 36232376, 2022). "As pro-inflammatory cytokines can influence anxiety- and depressive-like behaviors, we analyzed the expression of TNF, IL-6, and IL-1β in the hippocampus." (PMID 36333302, 2022). "The conditional deletion of TNF from microglia prevented the stress-induced increase in hippocampal TNF, and also prevented a stress-induced increase in anxiety-like behavior." (PMID 36104437, 2022). "This TNF-mediated potentiation correlates with the stress-induced increase in anxiety-like behavior, and blocking TNF-signaling even hours after the stressor reverses both the synaptic potentiation and anxiety-like behavior." (PMID 36104437, 2022). "In patients with baseline hs-CRP > 5 mg/L, a monoclonal antibody drug directed at TNF-α (infliximab) can significantly reduce depressive symptoms, including depressed mood, anxiety, and suicidal ideation." (PMID 36186850, 2022). "Other studies in rodents have also demonstrated that TNF-α is closely related to the occurrence of anxiety symptoms." (PMID 36106141, 2022).
Anxiety (continued). "A recent study found that maternal OCD was related to a significantly higher level of cord blood TNF-α which also was positively correlated with maternal anxiety level." (PMID 36061386, 2022). "Further, sustained hippocampal TNF signaling is required to maintain the synaptic potentiation and the increase in anxiety-like behavior induced by acute stress." (PMID 36104437, 2022). "We, therefore, conclude that acute stress induces on-going TNF signalling within the ventral hippocampus that is required to maintain the synaptic and behavioral outcomes of the stressor, in particular anxiety-like behaviours." (PMID 36104437, 2022). "Oral administration of HM improved chronic restraint stress-induced anxiety in Elevated Plus maze test along with reduction of plasma corticosterone and TNF-α levels." (PMID 35204117, 2022). "For instance, minocycline, an antibiotic with anti-inflammatory properties, reduced the level of IL-1, IL-6 and TNF-α and ameliorated anxiety behaviors after trauma exposure." (PMID 35625844, 2022). "Treatment TNFα inhibitors have been shown to improve the symptoms of anxiety in patients and animals." (PMID 33767622, 2021). "A study of chronic colitis that induced an anxiety-like behavior in rats showed increased TNF-a levels and concurrent suppressed expression of brain-derived neurotrophic factor." (PMID 33498197, 2021). "The administration of anti-TNF-a rescued the anxiety-like symptoms though expression of the brain-derived neurotrophic factor remained low." (PMID 33498197, 2021). "Meanwhile, local infusion of TNFα-neutralizing antibody in the amygdala reverses anxiety-like behavior in mice with persistent inflammatory pain." (PMID 34025342, 2021). "Among them, esculetin attenuates LPS-induced anxiety and depressive-like behavior and plays a role in inhibiting corticosterone and pro-inflammatory cytokines interleukin (IL)-1β, -6, and TNF-α." (PMID 34220460, 2021). "Reversal of N/OFQ up-regulation in the hypothalamus by anti-TNF-α antibody treatment in males is consistent with alleviation of allodynia, hyperalgesia, and anxiety-like symptoms." (PMID 34512420, 2021). "8-OaS also blocked microglia activation and reduced the phosphorylation of p38, c-Jun N-terminal kinase (JNK), NF-κB p65, and tumor necrosis factor alpha (TNF-α) in the BLA of anxiety mice." (PMID 32367473, 2020). "The baseline TNF-α levels significantly correlated with the decreased HAM-D-24 scores, particularly for the depressive symptoms of anxiety/somatization and weight loss." (PMID 33364982, 2020). "Some drugs prescribed for RA, such as anti-TNF-α medications, seem to have beneficial effects on anxiety symptoms, and their discontinuation is related to the worsening of anxiety." (PMID 33365319, 2020). "Accordingly, the preventive blockade of TNF-α signaling by intracerebroventricular treatment with an anti-TNF-α antibody rescued both anxiety-like behavior and synaptopathy in the EAE model." (PMID 32655374, 2020). "The serum TNF-α and IL-6 concentration were higher in patients with IBS-D than in the healthy controls, and the anxiety scores were associated with a high concentration of TNF-α." (PMID 33092151, 2020). "Fittingly, 8-OaS inhibited this signaling pathway in both anxiety models, resulting in the decreased expression of NF-κB p65 and TNF-α." (PMID 32367473, 2020). "This note is supported by the finding that, 12/15-lipoxygenase overexpression elevates central SYN levels and triggers anxiety-related behavior and that TNF-α stimulates SYN expression in cultured endometrial stromal cells in a dose-dependent manner." (PMID 33239680, 2020). "In our two anxiety models, TNF-α expression in the BLA was increased in both the forced swimming and the CFA injection condition." (PMID 32367473, 2020). "LPS-induced acute-sickness behavior, including anxiety- and depressive-like behavior was prevented by attenuating among TNF-α, IL-1β, and IL-6 levels of brain and plasma of mice." (PMID 31213027, 2019).
Anxiety (continued). "Virally-mediated over-expression of S1PR3 in the mPFC produces a resilient phenotype whereas its knock-down produces a vulnerable phenotype, characterized by increased anxiety- and depressive-like behaviors, and these effects are mediated by TNFα." (PMID 31316053, 2019). "A strongly negative correlation was observed between cytokines (PAF, IL‐6, and TNF‐α) and anxiety‐like behavior (time spent in open arm and exploration time of central regions)." (PMID 29201553, 2017). "TNF-α levels have consistently been shown to be elevated in patients with anxiety disorder and in animals with anxiety-like behaviours." (PMID 28336920, 2017). "The intracerebroventricular (ICV) injection of PGRN or intraperitoneal injection of TNFα synthesis blocker thalidomide (25 mg/kg), prevented the memory impairment and anxiety behaviors induced by S-DEP." (PMID 28300056, 2017). "TNF‐α was elevated in the hippocampi of the anxiety groups, IL‐6 and TNF‐α were also significantly increased in the plasma of the subjects with signs of anxiety." (PMID 29201553, 2017). "The presence of associations between both IL-6 and TNF and investigatory behavior suggest that interactions between these two cytokines may mediate initial social investigation, possibly through changes in anxiety and aggression related responses to social interaction." (PMID 28753980, 2017). "In the present study, we found that the systemic treatment of thalidomide reversed the memory impairment and thigmotaxis/anxiety-like behaviors induced by sleep deprivation, thus confirming the functional role of the TNFα in the sleep deprivation." (PMID 28300056, 2017). "Treatment with exogenous PGRN or inhibitor of TNFα (thalidomide) reversed the long term memory impairment and anxiety-like behaviors." (PMID 28300056, 2017). "Individuals with lower serum ω3 or with a higher ω6/ω3 ratio (ω6 has proinflammatory effects) have significantly higher stress-induced anxiety levels and TNF-α and IFN-γ responses compared to those with higher serum ω3 and a lower ω6/ω3 ratio." (PMID 26881136, 2016). "More recently, depletion of Treg cells in wild-type mice potentiated depressive-like and anxiety-like behaviours, as well as serum IL-6 and TNF levels following chronic restraint." (PMID 25986444, 2015). "Significant increases in brain levels of both IL-1β and TNFα were observed only in female offspring from HFD/HFD dams that were also the only group to display increased anxiety and decreased sociability." (PMID 25212412, 2014). "In conclusion, long-term Ω-3 supplementation coupled with Ω-6 restriction was demonstrated to increase anxiety, improve cognitive function, reduce TNF-α expression and enhance neuronal progenitor proliferation in unchallenged mature adult (7 month old) mice." (PMID 25484856, 2014). "Our results show that a higher Ω-3:Ω-6 PUFA diet ratio increased hippocampal PUFA, increased anxiety, improved hippocampal dependent spatial memory and reduced hippocampal TNF-α levels compared to a low Ω-3:Ω-6 diet." (PMID 25484856, 2014). "Together, these studies support the notion that TNF-α may play a critical role in the pathophysiology of anxiety, underscoring the importance of further investigating inflammatory pathways as potential targets for intervention." (PMID 40485934, 2025). "Furthermore, significant interactions between TNF-α concentrations and sex were found for both total anxiety and social anxiety symptoms." (PMID 40485934, 2025). "TNF-α with correlative JAK2-STAT3 signaling pathway plays a major role in the inflammatory response of neurons in the prefrontal cortex, which in turn is strongly linked to anxiety development." (PMID 39410900, 2025). "We hypothesise that TNFα, fibrinogen, cortisol, and anxiety will mediate the relationship between BMI z‐score and poorer EF." (PMID 40650919, 2025).